IL2 (interleukin 2)
Diseases named in the same sentence as IL2 in open-access papers (continued):
Sharing a sentence is not in itself a finding about the gene and the disease.
tumor (continued). "Imbalance of the IL-2/sIL-2R system is capable of inducing abnormalities of the immune function of tumor cells in the body, resulting in the immune escape of tumors." (PMID 24748984, 2014). "B16-OVA-USP18 tumor-cell coculture significantly increased OT-1 T-cell proliferation, but also increased OT-1 T-cell secretion of IL-2 and IFN-γ." (PMID 24884733, 2014). "Treatment of mice with FTY720 to block new T cell trafficking from secondary lymphoid structures still enabled restoration of IL-2 production and proliferation by intratumoral T cells, and also retained most of the tumor growth control." (PMID 24829760, 2014). "Tumor-reactive clones were then generated and both the bulk population and selected clones derived thereof suppressed naïve T cell proliferation, IL-2 secretion, and DC maturation." (PMID 25477885, 2014). "IL-2 signaling exerts significant, yet divergent, regulatory effects on Th17 and Treg cells in the tumor." (PMID 24987392, 2014). "Kirschner and Panetta presented a mathematical model describing the dynamics between tumor cells, immune-effector cells, and IL-2." (PMID 25140193, 2014). "The T cell proliferates in response to autocrine signals from IL-2 and IL-4 resulting in an anti-tumor effect." (PMID 26056588, 2014). "The low frequencies are explained by the prevention of NK cell attack onto “self”-MHC-expressing tumor cells from the inhibitory KIRs or the expansion of regulatory T cells induced by IL-2." (PMID 24741604, 2014). "In contrast, when the peripheral-derived γδ T cells were cultured with irradiated autologous tumor cells in the presence of IL-2 and IL-15, they showed markedly increased proliferation (defined as tumor-activated γδ T cells) (n = 9, P < 0.01)." (PMID 24741609, 2014). "In this study it was demonstrated that recombinant vaccinia virus expressing interleukin-2 invoked anti-tumor cellular immunity in an orthotopic murine model of HNC." (PMID 24886178, 2014). "The third case study comprises a model of interactions between effector cells, tumour cells, and IL-2 and TGF- molecules." (PMID 24752131, 2014). "Treatment with Ad-hLF increased the levels of serum interferon-γ, serum interleukin-2 (IL-2) and tumor necrosis factor-α, and decreased the levels of serum IL-4 in tumor-bearing mice." (PMID 24520300, 2014). "One (EC0294) of four tested-conjugates, in combination with IL-2 and IFNα, markedly improved survival of M109 tumor bearing mice for more than 100 days; two of the treatments, EC0293 and EC0294, gave 40 and 60% cure rates, respectively, among these mice." (PMID 24949488, 2014). "Such T cells from excised tumor tissues or patients’ blood are selectively expanded in vitro on syngeneic Ag presenting cells (APCs) expressing the tumor Ag with cytokines like IL-2 and then transferred back into the patients." (PMID 24647439, 2014). "These CD4+ T-cells would have likely produced Th1 cytokines, like IFNγ and IL-2, stimulating X5563-specific effector T-cell clones already present in the animal allowing for cytotoxic responses to the tumor." (PMID 24949488, 2014). "Autologous transfer of tumor infiltrating lymphocytes (TIL) can mediate durable regression of metastatic melanoma when administered with IL-2 therapy in patients that have been lymphodepleted." (PMID 25562142, 2014). "We noted a significantly increased infiltration of CD8+ cells, while the CD4+ and IL2+ cell count in the tumor environment of IFNγ-ADSC treated mice remained constant." (PMID 25428727, 2014). "This phenomenon was observed in a murine NB model, where recurrent tumors developed after an NK-dependent anti-tumor response induced by a humanized IL-2 immunocytokine targeted to GD2." (PMID 24575100, 2014). "In these trials, lymphocytes [either tumor-infiltrating lymphocytes (TIL) or gene-engineered PBL] are often expanded with high dose IL-2 (6000 IU/ml) and soluble OKT3 (anti-CD3), or are expanded with magnetic beads decorated with CD3 and CD28 agonists." (PMID 24987392, 2014).
tumor (continued). "Second, hemocyanins are slowly processed, and third, hemocyanins stimulate T-helper cell responses, supporting the secretion of cytokines such as IFN-γ and IL-2 by tumor reactive T cells localized in the regional lymph nodes." (PMID 24466345, 2014). "From this we can check that during 5 days, tumor size is highly sensitive to parameters a (tumor growth), d (strength of immune system), and α1 (rate of IL-2 and DC induced CD8+T cell activation) in order of list." (PMID 25140193, 2014). "STAT-5 is required for IL-2-induced cell cycle progression in T cells and is required for antigen-induced T-cell recruitment into tumor tissue." (PMID 24883189, 2014). "In a murine model, Tang and colleagues showed that transfer of the CX3CL1 gene into tumor cells elicited tumor-specific cytotoxic T cells and increased production of IL-2 and IFN-γ in tumor tissue leading to inhibition of HCC growth." (PMID 24799766, 2014). "Tumor-infiltrating lymphocytes (TILs), isolated form freshly resected tumors, can mediate lysis of tumor cells after in vitro incubation with IL-2." (PMID 24741604, 2014). "The presence of IL-2 in several cancer cells has been published; therefore, the importance of IL-2 lies in its being a growth factor of tumor cervical cell lines." (PMID 25309919, 2014). "Case study 2 referred to the investigation of a scenario containing interactions between effector cells, cytokines IL-2 and tumour cells." (PMID 24752131, 2014). "At the same time, CD4+CD25+ Treg cells remained IL-2 responsive and their inhibitory function was enhanced by tumor exosomes." (PMID 24639679, 2014). "This is in line with findings reporting an inhibition of IL-2-mediated up-regulation of CD25 by tumor exosomes selectively in NK cells and CD8+ T cells." (PMID 24639679, 2014). "We have previously demonstrated that immunotherapy combining agonistic anti-CD40 and IL-2 (IT) results in synergistic anti-tumor effects." (PMID 25119341, 2014). "DCs were prepared from the mononuclear cells isolated from patients using IL-2/GM-CSF and loaded with tumor antigens; CIK cells were prepared by incubating peripheral blood lymphocytes with IL-2, IFN-γ, and CD3 antibodies." (PMID 24699863, 2014). "It was recently reported that IL-15 stimulation resulted in a significant enhancement of CIK cell-mediated cytotoxicity against tumor cells compared to IL-2-induced CIK cells." (PMID 24748966, 2014). "Human tumor cell lines were also found to produce exosomes that were capable of inhibiting IL-2-stimulated NK cell proliferation." (PMID 24639679, 2014). "Our previous study have shown that CIK cells stimulated with combination of IL-2 and IL-15 displayed improved proliferation capacity and tumor cytotoxicity." (PMID 25108500, 2014). "Survival and anti-tumor response were analyzed by diagnosis, severity of toxicity, number of IL-2 cycles and subsequent therapy." (PMID 24855563, 2014). "Using a murine model, it was shown that localized TDLN targeted therapy using liposomes functionalized with anti-CD137 and IL-2 can control tumor progression by activating a systemic anti-tumor response." (PMID 25380524, 2014). "Data is uniformly collected for every cycle, at the standard tumor assessment after each HD IL-2 course (2 cycles) and at a standard interval follow up (approximately every 6 months)." (PMID 25562142, 2014). "The patient recovered well and received interleukin-2 (IL-2) therapy postoperatively, but died 4 months after surgery from intra-peritoneal recurrence of the tumour." (PMID 25430016, 2014). "In contrast, as early as three days after therapy initiation, a marked increase in the capacity of tumor-infiltrating CD8+ T cells to produce IL-2 and to proliferate was found in all groups treated with the effective combinations." (PMID 24829760, 2014).
tumor (continued). "As it has been previously shown by others and us in the tumor T cell line Jurkat that expression of HCV-core blocks IL-2 production, we aimed to test the effect of HCV-core in primary, non-tumor T cells." (PMID 24465502, 2014). "T cell proliferation and IL-2 production stimulated by the tumor lysates or the purified recombinant protein were specific since splenocytes from mice given a placebo (PBS) immunization failed to respond to these stimuli." (PMID 25340750, 2014). "The major biologic correlate to this improved efficacy was restored IL-2 production and proliferation of tumor-infiltrating CD8+ T cells." (PMID 24829760, 2014). "Studies have shown that tumor preconditioning with IL-2 and Treg depletion using a depleting antibody or low-dose cyclophosphamide led to increased intratumoral uptake of systemically delivered reovirus or vesicular stomatitis virus." (PMID 25101244, 2014). "As tumor antigens are weakly immunogenic, dendritic cell vaccination and IL-2 treatment are usually used to increase CTL activity clinically." (PMID 24884733, 2014). "Specifically, co-administration of IL-2 has been reported to enhance the anti-tumor immune responses of therapies targeting OX40 (CD134), GITR (CD357) and 4-1BB (CD137)." (PMID 25411639, 2014). "We tested three iHsp90s (17-AEP, CCT and PU-H71) in a cell-based assay in which increased IL-2 secretion by responding T cells is a manifestation of tumor cell recognition." (PMID 25503774, 2014). "It has also been demonstrated that NK cells were unable to be activated, in response to Interleukin 2-mediated blocking by tumor-derived exosomes, and that tumor-derived exosomes suppress T-cells via induction of adenosine." (PMID 24904836, 2014). "Case study 3 includes the influence of the cytokine TGF- in the interactions between effector cells, cytokines IL-2 and tumour cells from the previous case." (PMID 24752131, 2014). "Using our B16 tumor model, we co-administered pmel-1 CTLs, Ad-USP18, IL-2 and dendritic cells into tumor." (PMID 24884733, 2014). "There, they evaluated the effects of repeated peritumoral local injections of human IL-2 secreting cells after surgical removal of the tumor followed by 192Ir-brachytherapy." (PMID 25506617, 2014). "Baseline VEGF levels have been suggested to predict anti-tumor response to high-dose IL-2 and to VEGFR-targeted therapies." (PMID 24829759, 2014). "Cytokines that foster activation of lymphocytes such as IL-2 or IL-15 have been evaluated in preclinical models and are currently tested in clinical studies to augment tumor-specific immunity." (PMID 24312302, 2013). "Case study 2 referred to the investigation of the interactions between effector cells, cytokines IL-2 and tumour cells, and only one scenario was considered." (PMID 23734575, 2013). "In an attempt to potentiate eosinophil survival and function and potentially decrease tumor growth, we added IL-2 (100 ng/ml), IL5 or a combination to the culture media." (PMID 23369060, 2013). "Chemokine addition alone showed additive anti-tumor effect, while the combination of chemokine plus IL-2/GM-CSF boosted the response even further." (PMID 24967094, 2013). "Case study 3 added complexity to the previous case study by establishing a mathematical model including the influence of the cytokine TGF-β in the interactions between effector cells, cytokines IL-2 and tumour cells." (PMID 23734575, 2013). "The second case study adds to the previous model the influence of IL-2 cytokine molecules in the immune responses of effector cells towards tumour cells." (PMID 23734575, 2013). "IL2-fed tumor-bearing mice served as positive control to estimate the anti-tumor property of calcarea carbonica." (PMID 24053127, 2013). "In a recent report, melanoma patients who had better response following treatment with high dose IL-2 plus vaccine had higher Treg frequencies portraying a correlation between Tregs and better response against tumor." (PMID 23874336, 2013).
tumor (continued). "The tumors grew well after the engraftment of Colo205-luc cells in the human IgG control group, thus the T cells and IL2 alone had little effect on retardation of tumor growth." (PMID 24086580, 2013). "For example, IL-2 is known to increase the antitumor efficacy of tumor lysate-primed dendritic cells transferred to mice." (PMID 24391824, 2013). "In the present study, we observed that the biologically active metabolite of vitamin D3 (1,25(OH)2D3), calcipotriol and FTY720 augment IL-2-activated NK cell lysis of tumor target cells K562 and RAJI with variable efficacies." (PMID 24169587, 2013). "IL-2, which belongs to the common γ chain family of cytokines, has been shown to promote T cell activation, proliferation and survival, and to induce tumor lysis by the expanded lymphocytes." (PMID 23402380, 2013). "Cytokines, especially IL-2, characterized as one of the most potent anti-tumor cytokines, are a potential therapeutic approach in PC." (PMID 24303367, 2013). "In vitro, it has been shown that exogenous IL-2 was necessary in order for modified T cells to have a marked effect on tumor growth." (PMID 23433424, 2013). "It is important to note that both IL-2 and IL-15 are highly efficient adjuvants that have been shown to enhance tumor-specific T cell responses." (PMID 24312302, 2013). "The decrease in EAC cell number was at equivalence with that observed in IL2-treated tumor-bearing mice." (PMID 24053127, 2013). "A recent study has also demonstrated that IL-2 controls the balance between Th-17 and Treg cells in the tumor microenvironment." (PMID 24344728, 2013). "We demonstrated recently that tumor antigen-specific T cells were maintained after aAPC/exogenous IL-2-based expansion of TIL." (PMID 23402380, 2013). "We found that by linking NKG2D to IL2, we were able to specifically deliver IL-2 to the tumor location, enhancing antigen-specific T-cell immune response and controlling tumor growth." (PMID 24354786, 2013). "HSP 70 expressing tumour cells are more sensitive to lysis mediated by IL-2 stimulated, transiently plastic adherent NK cells, as compared to HSP 70 membrane negative tumour cell." (PMID 23662149, 2013). "The EpCAM antibody component of huKS-IL2 targets IL2 to EpCAM-positive tumors for the generation of cytotoxic T-cells and activation of the innate immune system, i.e. natural killer (NK) cells, in the tumor microenvironment." (PMID 23320927, 2013). "The third case study comprised interactions between effector cells, tumour cells and two types of cytokines, namely IL-2 and TGF-β." (PMID 23734575, 2013). "Subsequently, we measured the levels of Ag-specific antibodies in tumor-bearing animals following injection of E7 DNA vaccines (pE7)+IL-2 cDNA (pIL-2) in combination with anti-4-1BB Abs." (PMID 24391824, 2013). "There are many cytokines secreted by aHSCs that are associated with tumor invasion and metastasis, ingcluding HGF, EGF, IL-1, IL-2, IL-6, MMP-2, MMP-9, TGF-β, TNF-α, VEGF and Wnt families." (PMID 23622143, 2013). "A mathematical model for the interactions between tumour cells, effector cells and the cytokine IL-2 was considered to investigate the potential contribution of building the model under an ABMS perspective." (PMID 23734575, 2013). "The second case study investigated is concerned with a mathematical model for the interactions between tumour cells, effector cells and the cytokine IL-2." (PMID 23734575, 2013). "Mice received radiation to the left lung, followed by systemic IL-2 therapy, which resulted in tumor reduction in both lungs." (PMID 24324970, 2013). "In conclusion, our data showed that combined stimulation through IL-2 and 4-1BB receptors with IL-2 from IL-2 cDNA and anti-4-1BB Abs, respectively, is critical for increasing tumor cure rates induced by E7 DNA vaccines." (PMID 24391824, 2013). "To estimate the immune-modulating effect of calcarea carbonica, we included know immunostimulatory cytokine IL2-treated tumor-bearing mice in the study." (PMID 24053127, 2013).
tumor (continued). "They subsequently showed that Hsp70-derived 14-mer peptide (TKD) in combination with IL-2 enhances the cytolytic activity of resting NK cells against tumor cells presenting Hsp70 on their cell membrane." (PMID 23476104, 2013). "They demonstrated that treatment with immune-complexes of IL2 + S4B6 mAbs (anti-IL2 mAb which interferes the binding of IL2 to the alpha chain of IL2 receptor), prevents vascular leak syndrome while inducing a potent anti-tumor response." (PMID 24376444, 2013). "This is an extension of the previous study, since it considers IL-2 as molecules that will mediate the immune response towards tumour cells." (PMID 23734575, 2013). "IL-2 activated NK cells kill tumor cells in vitro and in vivo by localizing to the tumor sites to elicit their cytotoxic action and they prolong the survival of tumor bearing mice." (PMID 23404428, 2013). "Effector cells activated with only OKT-3/IL-2 in cohort i displayed a marginal tumor-suppressive effect, which was probably attributable to xenoreactivity." (PMID 23441216, 2013). "This would result from the expression of a high affinity CD25 receptor for IL-2 on the Treg surface that sequesters free IL-2 in the tumor surroundings, preventing this cytokine from reaching antitumor CTLs." (PMID 23533456, 2013). "The first term p3ET(g4+T)(1+αS) represents IL-2 production which reaches a maximal rate of p3 in the presence of effector cells stimulated by their interaction with the tumour cells." (PMID 23734575, 2013). "In the transition rate calculations, the variable TotalTumour corresponds to the total number of tumour cell agents, the variable TotalEffector is the total number of effector cell agents and TotalIL_2 is the total number of IL-2 agents." (PMID 23734575, 2013). "Previously, we used NKG2D to specifically deliver IL-2 to Rae-1 expressing TC-1 tumors in tumor-bearing mice." (PMID 24354786, 2013). "In DT-treated mice, significantly more CD4+CD154+ T cells expressed the cytokines IFN-γ, TNF-α, and IL-2 than in mice receiving only tumor cells." (PMID 22890822, 2013). "These events depress mitogen-induced lymphocyte proliferation and interleukin-2 production, thereby impeding antitumor immunity, and also up regulate vascular endothelial growth factor, thereby accelerating tumor angiogenesis." (PMID 24098431, 2013). "Incubation of peripheral blood lymphocytes with TKD peptide plus a low dose of IL-2 initiates the cytolytic and migratory capacity of NK cells toward Hsp70-membrane-positive tumor cells in vitro and in a xenograft tumor mouse model." (PMID 23476104, 2013). "The final case study comprises an ODE model of interactions between effector cells, tumour cells, and IL-2 and TGF-β molecules." (PMID 23734575, 2013). "The current approach for the expansion of TIL for ACT involves the expansion of TIL from small tumor fragments or biopsies by exposure to high-dose IL-2, irradiated feeders and CD3 ligation via an anti-CD3 antibody (also called REM)." (PMID 23402380, 2013). "Co-delivery of pE7+IL-2 cDNA increased tumor cure rates from 7% to 27%, whereas co-delivery of pE7+IL-2 cDNA with anti-4-1BB Abs increased tumor cure rates from 27% to 67% and elicited long-term memory responses." (PMID 24391824, 2013). "Another study tested the combination of tumor irradiation with IL-2 therapy in an animal model looking at lung metastasis from renal adenocarcinoma." (PMID 24324970, 2013). "Systemically administered cytokines, such as interleukin-2 (IL-2), activate the immune system to enhance immune-mediated responses against the tumour, thereby diminishing its metastatic potential." (PMID 23927575, 2013). "A decrease in NK cell proliferation in response to IL-2 was also observed after treatment with exosomes derived from different tumor cell types (breast and melanoma) due to the inhibition of the JAK-STAT signaling." (PMID 24400010, 2013).